MUC16 (mucin 16, cell surface associated)
Diseases named in the same sentence as MUC16 in open-access papers (continued):
Sharing a sentence is not in itself a finding about the gene and the disease.
tumor (continued). "Tumor cells that survived the NKL challenge expressed higher levels of MUC16 indicating selective lysis of MUC16low targets." (PMID 20089172, 2010). "This antibody both induces ADCC (antibody-dependent cellular cytotoxicity) against tumor cells that express mesothelin as well as blocks the MUC16/mesothelin interaction." (PMID 20350313, 2010). "We have studied the effects of one particular factor produced in high quantities by the tumor cells, MUC16, and its effect on the cytolytic function of human NK cells." (PMID 20089172, 2010). "Furthermore, the extensive glycan structures of MUC16 create a physical barrier on the surface of tumor cells, hindering effective immune synapse formation between immune cells and tumor cells." (PMID 40655139, 2025). "Somatic mutations enriched in the low-risk group (e.g., CDKN2A, MUC16, DNAH8) may reflect increased neoantigen load, enhancing tumor visibility to the immune system." (PMID 40909289, 2025). "Therefore, the development of therapeutic strategies targeting the interactions between MSLN and MUC16, along with the exploration of their combined application with existing therapies, is anticipated to yield new breakthroughs in tumor therapy." (PMID 41400642, 2025). "In epithelial ovarian cancer cells, MUC16 plays a key role in tumor growth and metastasis." (PMID 40457720, 2025). "Mutations in MUC16 and TTN were associated with associated with improved overall survival (OS), and the mutation status and number of mutations in MUC16 and TTN were effective predictors of tumor mutational burden (TMB)." (PMID 40567896, 2025). "Clinically, Muc16 is upregulated in PDAC tumor tissues and confers poor survival in patients." (PMID 39346763, 2024). "Muc1-Bi antibodies recruit NK cells to drive effective and specific cell killing of MUC1-overexpressed tumor cells.Therefore, we hypothesized that bifocal antibodies targeting both MUC16 and CD16 would have similar effects in tumors." (PMID 38758220, 2024). "However, increased expression of Muc16 on solid tumors contributes to tumor progression and metastasis while enabling immune escape by directly suppressing natural killer cells and macrophages." (PMID 39346763, 2024). "Dysregulated expression and glycosylation of MUC1 and MUC16 in cancer, notably affecting immune modulation and metastasis, impair dendritic cell function, resulting in heightened immunosuppression and advancing tumor progression." (PMID 38361923, 2024). "MUC16’s role in the tumor immune microenvironment is equally significant." (PMID 38361923, 2024). "Tumors with MUC16 mutations exhibit heightened immunogenicity, reflected by an increased proportion of CD8A and Programmed cell death 1 ligand 1 (PD-L1)-positive cells in the tumor microenvironment compared to wild-type tumors." (PMID 38758220, 2024). "This suggests that high expression of MUC1 and MUC16 aids tumor cell immune evasion." (PMID 38361923, 2024). "No common MUC16 recurrent somatic mutations involved in the development of NB or other tumor types have been validated in other studies." (PMID 39338204, 2024). "We interpret these results to indicate that CAR T cells prepared with a ligand-binding domain of MUC16 based on mesothelin may potentially evade host immune responses to scFv and maintain anti-tumor activity." (PMID 38637885, 2024). "Since MUC16 can promote tumor progression by directly inhibiting NK cells in tumors, we hypothesized that bispecific antibodies combined with NK cells may be more effective." (PMID 38758220, 2024). "Moreover, tumor-related gene mutations such as TTN, MUC16, and KRAS with a higher number in groups were also enriched in distinct groups." (PMID 38488909, 2024). "As shown in the waterfall plot, there are variations in the tumor mutational burden (TMB) of two subtypes, and the frequencies of TTN, CSMD3, MUC16, RYR2, LRB1P and ZFHX4 mutations in the high-risk group were considerably higher than those in the low-risk group." (PMID 38345559, 2024).
tumor (continued). "In tumor immune microenvironment research, the roles of MUC1 and MUC16 in regulating mechanisms by which tumor cells evade immune surveillance, and how these proteins influence immune escape and treatment response through different pathways, are currently focal points of investigation." (PMID 38361923, 2024). "Therefore, we investigated MUC16 expression after NCT in patient samples to reflect tumor heterogeneity and clinical treatments." (PMID 39456534, 2024). "To distinguish cancer cells from non-cancerous cells in the organoids and the stromal cell cultures, respectively, we used established tumor marker genes, including PAX8, MUC16 (encoding CA-125) and EPCAM, collectively referred to as PAX8+ cells (Online “Methods”, Suppl." (PMID 39362905, 2024). "Further supporting our proposed mechanism, N-cadherin levels were high in MUC16-high tumor sections with a strong positive correlation of N-cadherin and MUC16 expression in primary PC tumors (P = 0.002, r = 0.84) and metastatic samples (P = 7.78e–13, r = 0.99)." (PMID 37567918, 2023). "Similarly, MUC13 and MUC16 are overexpressed in HCC and other liver-associated cancers, promoting tumor growth and metastasis." (PMID 36980526, 2023). "The expression of MUC16 is mostly discussed in the context of tumor epithelial cells in PDAC." (PMID 36816942, 2023). "The stronger affinity of MUC16 with specific immune cells expressing Siglec-9 may change the specific immune microenvironment and provide new directions for tumor immunotherapy, which remains to be further studied." (PMID 37644468, 2023). "The expression of different mucins, like MUC1, MUC4, and MUC16, which are upregulated during cancer progression, may also inhibit apoptosis of tumor cells." (PMID 37207152, 2023). "Thus, MUC16 plays a key role in promoting tumorigenesis and tumor proliferation, suggesting that it is a promising target for immunotherapy." (PMID 36979400, 2023). "Novel tumour-associated mutations in CIITA and MUC16 were recorded in the Indian cohort." (PMID 37091785, 2023). "In parallel, the scRNA data from 15 PDAC tissues samples also showed higher infiltration of cells expressing SMC/fibroblast markers (PDPN, COL5A1, COL22A1, TIMP3, SPARC, WT1, GFPT2) in samples with higher proportions/fractions of MUC16-expressing tumor (epithelial) cells (n = 7)." (PMID 36816942, 2023). "On the other hand, the tumor tissues of the whole-body knockout model of MUC16 showed downregulation of cytoskeletal, smooth muscle contraction, myofibril organization, and focal adhesion pathways besides profound transcriptional changes to fibroblast subtype markers." (PMID 36816942, 2023). "The role of MUC16 on neutrophils in the tumor microenvironment remains to be further explored." (PMID 37644468, 2023). "MUC16 (CA125) is commonly used as a tumor marker for EOC screening." (PMID 37644468, 2023). "Therefore, specific staining and shrinkage of patient-derived tumor organoids (PDTOs) by ch5E6 indicates its ability to recognize and target clinically present forms of MUC16." (PMID 37567918, 2023). "MUC16 regulates tumor cell proliferation by mediating glucose transporter 1 (GLUT1)." (PMID 37664708, 2023). "To date, MUC1 and MUC16 have been reported to be specific tumor antigens for Siglec-9." (PMID 37444515, 2023). "However, the role of MUC16 on neutrophils in the tumor microenvironment remains to be further explored." (PMID 37644468, 2023). "MUC16 (CA125) is a commonly used tumor marker for EOC screening." (PMID 37644468, 2023).
tumor (continued). "In contrast to the C1/MES subtype, the C4/DIF molecular subtype was described as having a low stromal response histologically and genetically, moderate immune infiltration in tumor and stroma and expression of markers of differentiation including E-cadherin, MUC16 and MUC1." (PMID 37858159, 2023). "89Zr-M16Ab showed early high uptake in MUC16-positive tumor xenografts in the NOD-SCID mice." (PMID 36559316, 2022). "Second, the roles of MUC16 and TTN mutations in the anti-tumor immune process were still unclear." (PMID 35568842, 2022). "The specificity of targeting and the high tumor uptake make our developed anti-MUC16 antibody a great contrast agent for non-invasive imaging and show potential for further development as radiopharmaceuticals for targeted therapy of MUC16-expressing cancers." (PMID 36559316, 2022). "The gene expression analysis of the full set of 11,003 samples from 33 TCGA tumor types identified three genes (MUC16, PAX8 and SOX17) that showed gene expression ranges of OSCA samples that did not overlap with the gene expression ranges of samples deriving from most of the other tumor types." (PMID 35954427, 2022). "This article also provides references for subsequent tumor therapy studies targeting MUC16." (PMID 35899441, 2022). "We also identified some gene mutations (ATRX, and MUC16) in different stemness subtypes, which might be potential targets for STS to regulate stemness of tumor cells." (PMID 35464409, 2022). "MUC16 can bind to membrane proteins of different tissues, promote metastasis in various cancer types, induce cell proliferation and metastasis, and protect tumor cells from chemotherapy." (PMID 35954348, 2022). "The S2 subtype of mesenchymal tumor cells overexpressed MUC16 and TNFRSF11B, which might lead to immune resistance." (PMID 36553542, 2022). "Moreover, IFN-γ induces the expression of PD-L1 inhibiting T cell effector functions promoting tumor progression and expression of MUC16 to promote tumor progression." (PMID 33669271, 2021). "MUC16 has been proposed to be a tumour biomarker of epithelial ovarian cancer." (PMID 33543559, 2021). "It has been reported that MUC16 mediates the interaction between tumour cells and immune cells." (PMID 33543559, 2021). "MUC16 expression depends on the Gal3 pathway to enhance tumor growth." (PMID 33580170, 2021). "We examined the effect of GLUT1 on MUC16‐induced cell proliferation and observed that GLUT1 overexpression could mimic the tumour‐promoting effects of MUC16." (PMID 33543559, 2021).
tumor (continued). "And the effect of glucose metabolite on immune cells in tumour microenvironment is worth further studying, this may explain why MUC16 can affect the regulation of immune responses, which is our next‐step research direction." (PMID 33543559, 2021). "All these results were proved the fact that MUC16 is a prognostic biomarker in EOC, maybe because of promoting effect of MUC16 on tumour cell proliferation." (PMID 33543559, 2021). "Pre-treatment with both parental antibodies resulted in the total lack of biodistribution of the 89Zr-labeled MUC16xCD3M bsAb, whereas pre-treatment with parental CD3 antibody resulted in distribution to the tumor site, due to recognition of MUC16 on tumor cells." (PMID 34257348, 2021). "Furthermore, the high expression of the MUC16 C terminal (MUC16c) reflects the high proportion of Treg in the tumor microenvironment, to some extent." (PMID 34490033, 2021). "Targeting MUC16 to develop anti‐tumour drugs has higher specificity than drugs target GLUT1." (PMID 33543559, 2021). "Although the promoting effect of mucin 16 (MUC16) on tumour progression has been reported, the potential mechanisms remain unclear." (PMID 33543559, 2021). "We demonstrated that antibody-mediated Gal3 blockade results in the predicted inhibition of tumor signaling pathways and tumor cell invasion, with evidence of anti-tumor activity observed in animal tumor models expressing MUC16 as a candidate glycoprotein partner." (PMID 33580170, 2021). "Although targeting MSLN region I (like the SS1 scFv does) blocks the MSLN tumor-promoting interaction with MUC16, a preclinical study suggested that MSLN region III is a better target as it mediated a stronger activation and cytotoxicity compared to CAR T cells targeting region I." (PMID 33588928, 2021). "Numerous in vitro and in vivo studies, as well as studies on humans, prove that targeting overexpressed molecules, such as mucin 16 (MUC16), annexin 2 (ANXA2), receptor tyrosine-protein kinase erbB-2 (HER2/neu) causes high tumour cells toxicity and decreased tumour burden." (PMID 33800608, 2021). "MUC16 knockout mice exhibit stalled tumour growth both in vitro and in vivo." (PMID 33322519, 2020). "MUC16 has been identified as a tumor biomarker and serves as novel target for cancer therapy." (PMID 32626534, 2020). "Studies on ovarian cancer cell lines showed that mesothelin is involved in tumor adhesion and metastasis based on its binding to MUC16 (also known as CA125), due to its rich glycosylation, where O-linked and N-linked MUC-16 oligosaccharides triggered heterotypic cell adhesion." (PMID 33344222, 2020). "In addition, MUC16 was verified to enhance tumour progression and immune regulation through the mTOR, c‐MYC, MAPK and JAK‐STAT pathways." (PMID 32745356, 2020). "In addition to its role in metastasis, MUC16 inhibits Natural Killer (NK) cell-mediated destruction of tumour cells." (PMID 33322519, 2020). "Given the immunoprotective role of MUC16 ectodomain, identifying how the tumor environment alters MUC16 expression and secretion in cancer-associated stromal cells may provide a new way to block immune evasion by tumors." (PMID 31039761, 2019). "Because pro-inflammatory cytokines have been previously shown to stimulate expression of membrane-bound mucins such as MUC1, MUC4, and MUC16 in tumor cells, we hypothesized that ascites could enhance MUC16 expression in HPMCs." (PMID 31039761, 2019). "Studies of MUC16 in other tumor types have indicated that MUC16 is a critical therapeutic target." (PMID 31822636, 2019). "Indeed, a peptide found in the VNTR domain on both csMUC16 and shedded MUC16 (sMUC16) is considered the tumor marker and is known as cancer antigen 125 (CA125)." (PMID 31143186, 2019).
tumor (continued). "Based on these observations, it appears that although both tumor and mesothelial cells may produce MUC16 under inflammatory conditions; the mechanisms regulating MUC16 expression differ between these cells." (PMID 31039761, 2019). "Our results showed that MUC16 is up-regulated in most of the tumor tissue samples analyzed." (PMID 30287783, 2018). "This MUC16 targeting system reduced the mass of neoplastic cells capable of adhering to parietal and visceral peritoneal surfaces at sites distant to the original tumor implant." (PMID 30287783, 2018). "FSH-MUC16.1-G-NP exhibited significantly enhanced tumor regression compared with MUC16.1-G-NP." (PMID 29542355, 2018). "Similarly, when compared to control, the MUC16 knockdown colo-357 cells show decreased tumor formation in pancreas and metastatic burden." (PMID 27382435, 2016). "In addition, we observed that MUC16 knockdown completely eliminated the metastatic tumor growth in diaphragm and intestinal wall, and also reduced the metastatic burden in spleen and peritoneum." (PMID 27382435, 2016). "This suggests that in vivo low cytokine levels diffusing throughout a tumor may strongly potentiate MUC16 expression." (PMID 26918940, 2016). "To corroborate the in vitro findings, we examined whether silencing of MUC16 affects tumor development in nude mice." (PMID 27382435, 2016). "Also, MUC16 knockdown decreases the tumor formation and metastasis in orthotopic xenograft mouse model." (PMID 27382435, 2016). "As a final confirmation, we examined the in vivo tumor growth of MUC16 transfected A2780 lines." (PMID 25965947, 2015). "Mutations identified from our study in genes such as MUC16, MUC2 and ODZ1 could shed new insights into metastasis-promoting pathways in tumor cells." (PMID 26555578, 2015). "Since MUC16 knockdown cells also demonstrate decreased secretion of lactate, which is known to regulate tumor cell motility, we next studied if supplementation of culture media with lactate could restore cell migration in MUC16 knockdown cells." (PMID 26046375, 2015). "We observed significant increase in c-MYC expression in MUC16-positive tumor samples." (PMID 26046375, 2015). "MUC16 knockdown downregulated the expression of hexokinase II (HK II), a key enzyme of glycolysis that is upregulated in several types of cancers and whose ablation leads to reduced tumor growth." (PMID 26046375, 2015). "MSLN also binds CA-125/MUC16 with very high affinity and may contribute to the adhesion of tumor cells in peritoneal metastasis." (PMID 25506917, 2014). "One potential reason for Oregovomab and Abgovomab being unsuccessful in inhibiting tumor growth is that these antibodies may conjugate with the circulating ectodomain of MUC16 reducing the amount of antibody available to target the cancer cells." (PMID 24886523, 2014). "All five patients who responded to the conjugate had high expression levels of MUC16 which underscores the importance of targeting strategies in increasing the effectiveness of cancer drugs by way of facilitating their efficient delivery to the tumor cells." (PMID 24447304, 2014). "The overall objective of our study was to investigate whether there is a differential expression of MUC16 during the progression and development of PC and to examine a possible correlation between MUC16 expression and tumor characteristics." (PMID 22066010, 2011). "Since it was first described in 1981, the biological function of ovarian cancer tumour antigen CA125/MUC16 has remained mostly unknown." (PMID 21326240, 2011). "Further, to determine whether there is a variation in MUC16 expression with the progression of PC, we compared its expression between PC tissues classified by tumor stage and grade." (PMID 22066010, 2011). "Additionally, MUC16 also is a potent inhibitor of natural killer cell mediated anti-tumor cytotoxic responses." (PMID 19538730, 2009).